PRMT5 (protein arginine methyltransferase 5)
Diseases named in the same sentence as PRMT5 in open-access papers (continued):
Sharing a sentence is not in itself a finding about the gene and the disease.
cancer (continued). "Despite being categorized as an essential gene based on the CRISPR viability score in the DepMap cancer cell line data, multiple independent reports highlighted that cancer cells have a greater dependence on PRMT5 activity than do nontransformed cells." (PMID 40091834, 2025). "Therefore, both type I PRMT and PRMT5 inhibitor treatments significantly repressed ERCC1 expression and activity levels in cancer cells." (PMID 38826355, 2025). "As such, the biosensor could serve to stratify the relative levels of PRMT5-bound SAM and MTA across various normal- and cancer cell populations." (PMID 41339334, 2025). "Furthermore, the combination of SCR‐7952 with SAM‐competitive or MTA‐cooperative PRMT5 inhibitors supported further investigation and potential development of an effective strategy for larger therapeutic windows on MTAP‐deleted cancers." (PMID 39309689, 2024). "EPZ015666 is a selective PRMT5 inhibitor that binds to the peptide-binding site, giving the compound a peptide-competitive and SAM-uncompetitive characteristic, and its antitumor role has been tested in several cancer cell lines." (PMID 39795118, 2024). "In MTAP-deleted cancer cells, the level of MTA is elevated which inhibits the methyltransferase activity of PRMT5 towards all of its substrates, increasing the sensitivity of cancer cells to further PRMT5 inhibition." (PMID 38612768, 2024). "The expression level of both PRMT5 and MEP50 is often elevated in human cancer." (PMID 38612768, 2024). "In addition, certain factors, such as protein arginine methyltransferase 5 (PRMT5), can activate NF-κB signaling, which in turn enhances glycolysis in cancer cells." (PMID 39834817, 2024). "Additionally, PRMT5 in NDRG2low ATL and cancer cells is hyperphosphorylated and translocated to the cytoplasm, where it binds to HSP90, thus contributing to the maintenance of a high function of its client proteins." (PMID 38474089, 2024). "Thus, the targeting of PRMT5/MEP50 activity significantly induced the suppression of cell growth and the degradation of client proteins AKT and NEMO in NDRG2low ATL and other cancer cells." (PMID 38474089, 2024). "The first generation of PRMT5 inhibitors that were developed did not demonstrate sufficient selectivity for MTAP-deleted cancer cell lines and resulted in intolerability from dose-limiting myelosuppression." (PMID 39337530, 2024). "PRMT inhibitors were initially reported in the early 2000s, and recently specific inhibitors were designed to specifically target PRMT3, PRMT4, PRMT5, and PRMT6 in preclinical cell culture animal models, revealing the therapeutic and pharmacological potential of targeting PRMTs in cancer." (PMID 39201539, 2024). "Those date all indicated that human cancers that do not express MTAP protein exhibit an apparent reduction of PRMT5 activity relative to MTAP‐expressing tumors." (PMID 39711357, 2024). "SAM-cooperative orSAM-competitive inhibitors of PRMT5 are not expected to be selectivefor MTAP-null cancers because they inhibit PRMT5 equally in MTAP-nulland MTAP WT cells, ultimately leading to a molecule with limited therapeuticindex." (PMID 38595098, 2024). "In this context, methylation of STAT3 by PRMT5 can promote activated tyrosine phosphorylation of STAT3, which may work to maintain continuous STAT3 activation in cancer cells." (PMID 38760429, 2024). "By targeting this interaction, PRMT5 inhibitors could effectively impair HNRNPA1’s tumor-promoting activities, thereby curbing cancer progression and offering new avenues for cancer treatment." (PMID 39341825, 2024). "Among nine members of PRMT family, PRMT5, PRMT1, and CARM1 are most highly expressed in cancer." (PMID 39711357, 2024). "Recently, targeting PRMT5, or MAT2A that impacts PRMT5 activity by producing SAM, has shown promise as a therapeutic strategy in oncology, generating synthetic lethality in MTAP-negative cancers." (PMID 37795443, 2023).
cancer (continued). "In particular, a previous work discovered that PRMT5 monomethylates ENO1 at R50 to regulate its LPS‐induced translocation from the cytoplasm to the cell surface of lung epithelial cancer cells, thereby affecting the invasive properties of cancer cells." (PMID 36999124, 2023). "In certain cancers, BRG1 has been observed to correspond with PRMT5 in that process." (PMID 36769189, 2023). "In cancer cells, the MTAP gene is frequently co-deleted with CDKN2A, and this results in MTA-mediated inhibition of the methyltransferase PRMT5; in line with this, the sensitivity to PRMT5 inhibitors is higher in cells with increased MTA levels." (PMID 37563469, 2023). "Increased PRMT5 expression in L-CNV may enhance NF-κB activation and proinflammatory cytokine production, as we have shown in progression of cancer and metastasis." (PMID 36720900, 2023). "In the current study, we investigated whether pharmacologic inhibition of PRMT5 downregulates DDR/DNA replication pathway genes and sensitizes cancer cells to chemotherapy and PARP inhibition." (PMID 37861290, 2023). "In MTAP-deleted tumors, increased intracellular concentrations of methylthioadenosine (MTA), the metabolite cleaved by the MTAP enzyme, couple with PRMT5, compete with SAM and, as a result, inhibit PRMT5’s enzymatic activity and contribute to the proposed synthetic lethality in these cancers." (PMID 37502925, 2023). "In a further exploration of non-coding genome regulation, protein arginine methyltransferase 5 (PRMT5) and the transcription regulator E2F1, both of which are overexpressed in many cancers, significantly influence lncRNA gene expression, leading to peptides associated with MHC class I proteins." (PMID 37760852, 2023). "PRMT5 is reported to positively correlate with DDR genes in 32 The Cancer Genome Atlas clinical datasets, which translates well to correlations we observed in in vitro cancer models (CCLE database)." (PMID 37861290, 2023). "Overall, our data point to an MYC/PRMT5/RNAPII axis that controls termination via RNAPII symmetrical dimethylation and contributes to rewiring the expression of genes altered by MYC overexpression in cancer cells." (PMID 36830948, 2023). "Levels of expression of PRMT5 and APE1 in OSCC tissues are highly correlated in cancer but not in normal tissues, suggesting that regulation of PRMT5 and APE1 were overridden by the extent of CNV in the PRMT5-APE1 genome region." (PMID 37887269, 2023). "Over the past decade, extensive studies suggest that PRMT5 functions as an oncoprotein in various cancers through both epigenetic and non-epigenetic mechanisms." (PMID 37400460, 2023). "PRMT5 is a protein with significant effects on cancer growth and is highlighted in this review to emphasize the role BRG1 plays alongside it, whether cancer growth or inhibition." (PMID 36769189, 2023). "PRMT5 is a stemness factor crucial in maintaining the balance between quiescence, proliferation, and generation for cancer stem cells and non-cancer cells." (PMID 38136401, 2023). "Likewise, PRMT1 shares common substrates with PRMT5, thus the dual inhibition of PRMT1 and PRMT5 results in potent anti-tumor activity in different cancer models." (PMID 36167829, 2022). "It would be interesting to investigate whether the mechanism of resistance to PRMT5-targeted therapies mediated by the oncogenic axis, MSI2/c-MYC/BCL-2, could be extrapolated to the other cancers." (PMID 36167829, 2022). "Our study suggests that PRMT5 and LSD1 function as a dual epigenetic modifier to promote Slug induced EMT program, suggesting that the inhibition of PRMT5 and LSD1 presents a potential therapeutic strategy against cancer metastasis." (PMID 35655230, 2022). "There are also ongoing clinical trials involving PRMT5 inhibitors in hematological malignancies, showing, once again, that PRMT inhibition might become a useful therapeutic tool for cancer treatment." (PMID 36358861, 2022).
cancer (continued). "~15% of all human cancers lack MTAP (MTAP-) and accumulate by 5–20 folds a metabolic derivative—5′-methylthioadenosine (MTA)—of S-adenosyl-l-methionine (SAM), the cofactor for PRMT5 catalytic activity." (PMID 36192627, 2022). "We investigated whether the inhibitory effect of 3039-0164 on PRMT5 affected the activation of the AKT, ERK, and mTOR signaling pathways to learn more about the mechanism of cancer inhibition and the inhibitory effect of 3039-0164." (PMID 36364261, 2022). "MYC is an essential molecular hub in CML pathophysiology and could actively participate in the dysregulation of PTBP1 and hnRNPA1 as well as PRMT5 and SRSF1, genes deregulated by MYC in other cancers." (PMID 36230624, 2022). "How PRMT5 impacts tumorigenesis and cancer progression through its regulation of gene expression is not well defined." (PMID 35624451, 2022). "However, PRMT5 is predominantly found in the cytoplasm of OPC and of several other cell types, such as cancer cells and stem cells." (PMID 35370564, 2022). "Finally, our findings position PRMT5 as a critical regulator of gp130/STAT3 signaling to control the growth and development of human cancer, which provides an important mechanism for the oncogenic role of PRMT5." (PMID 34026434, 2021). "Besides, several PRMT5 inhibitors, including DS-437, LLY-283, CMP5, HLCL-61, C220 and PR5-LL-CM01, have been also used to treat different types of tumors, including human cancer cells." (PMID 34522232, 2021). "MTDIA causes a physiologic inactivation of MTAP and may also have efficacy in combination with inhibitors of MAT2A or PRMT5, known synthetic-lethal interactions in MTAP−/− cancer cell lines." (PMID 33893330, 2021). "Like PRMT5, SND1 is upregulated in many different cancer types." (PMID 33768972, 2021). "In addition, upregulation of PRMT5 activates PI3K, AKT, mTOR/eIF4E, and NF-κB signaling, contributing to the proliferation of cancer cells." (PMID 34006904, 2021). "While the role that PRMT5 plays in the development of HCC is largely circumstantial—elevated PRMT5 levels clearly correlate with the promotion of HCC and poor prognosis of these cancer patients—its effector molecule, SND1, is more solidly implicated as a driver of HCC." (PMID 33768972, 2021). "The physiologic impact of MTDIA on tissue metabolite levels and arginine methylation were also determined, since elevated MTA can potentially interact with other targets including type 1 PRMTs, PRMT5 and MAT2A by mimicking the metabolic physiology observed in MTAP−/− cancer cell lines." (PMID 33893330, 2021). "Interestingly, combined PRMT5 and type I (asymmetric) PRMT inhibition exhibit combinatorial effects in blocking cancer cell proliferation and xenograft tumor growth." (PMID 34109280, 2021). "With some exceptions the epigenetic drugs have not had widespread utility across cancers, but the field is relatively new and very recent compounds such as PRMT5 inhibitors are showing great promise in clinical trials." (PMID 34829820, 2021). "PRMT5 inhibition may enhance immunogenicity in PDAC, based on the predicted impact on the PDAC microenvironment and effects reported in other cancers." (PMID 34680285, 2021). "PRMT5 expression and SDMA level were significantly higher in cancer cells than in normal cells." (PMID 34522232, 2021). "This outcome is not surprising, as PRMT5 plays an essential role in cancer stem cell survival, mRNA splicing, and DNA repair processes." (PMID 34006904, 2021). "Interestingly, MTAP-deleted cancer cells accumulate the metabolite methylthioadenosine (MTA), which is a high-affinity inhibitor of PRMT5 activity." (PMID 33691794, 2021). "Among several PRMT5 inhibitors, PRT811 was shown to be brain penetrant in preclinical studies, and an open-label phase 1 study in patients with advanced cancers including solid tumors, CNS lymphoma, and/or high-grade gliomas is actively recruiting (NCT04089449)." (PMID 34769221, 2021).
cancer (continued). "In control lymph nodes from dogs without cancer (n = 40), PRMT5 immunoreactivity was weak and expressed only in the cytoplasm." (PMID 33989303, 2021). "We then evaluated whether PRMT4, PRMT5 and PRMT7-regulated alternative splicing events are involved in cancer cell growth." (PMID 33782401, 2021). "A previous study has shown that PRMT5 directly methylated E2F1 and regulates the cell cycle, which is required for gating the function of E2F1, suggesting that E2F1 methylation by PRMT5 leads to cancer cell cycle progression." (PMID 33495409, 2021). "However, patients with both high PDCD4 and PRMT5 demonstrate poor prognoses, suggesting that arginine methylation of PDCD4 by PRMT5 decreases the ability of PDCD4 to suppress cancer cell growth." (PMID 34006904, 2021). "Protein arginine methyltransferase 5 (PRMT5) complexed with methylosome protein 50 (MEP50)/WD repeat domain 77 (WDR77) can catalyze H3 and H4 arginine methylation, leading to the activation of EMT markers and carcinoma cell metastasis." (PMID 34298613, 2021). "However, due to proximity to CDKN2A on Chr9p21, MTAP is co-deleted with CDKN2A in 15-40% of human cancers, resulting in accumulation of unmetabolized MTA and attenuation of endogenous PRMT5 activity." (PMID 32743345, 2020). "In this study, our studies describe a possible mechanism, at least in part, underlying these oncogenic functions of PRMT5; the symmetric dimethylation of 53BP1 by PRMT5 results in stabilization of its protein level and promotion of NHEJ efficiency in cancer cells." (PMID 32759981, 2020). "In general, high levels of PRMT5 and E2F1 occurred in a range of cancers." (PMID 32709847, 2020). "Both PRMT5 and YBX1 serve as a potential therapeutic target for cancer treatment." (PMID 33375283, 2020). "Since MTAP is frequently deleted in human cancers due to its chromosomal proximity to CDKN2A, it was also speculated that inhibitors of PRMT5 could be utilized in potential therapy for MTAP/CDKN2A‐deleted tumors." (PMID 33155773, 2020). "Among nine members of PRMT family, PRMT5, PRMT1 and CARM1 are most highly expressed in cancer (621 cancer cell lines from cancer cell line encyclopedia database) and such high expression is correlated with worse prognosis of patients in a number of cancer types." (PMID 32743345, 2020). "Moreover, protein expression of GLI1 was enhanced by MEP50/PRMT5 and expression of MEP50, PRMT5, and GLI1 target genes was upregulated in HH-expressing cancers." (PMID 30675521, 2019). "Treatment with OICR-9429, a small-molecule antagonist of the WDR5-MLL interaction, inhibits the β-catenin/JDP2/PRMT5 complex-reestablished GSH metabolism, leading to a lethal increase in the already-elevated levels of ROS in the genotoxic-agent treated cancer cells." (PMID 31434880, 2019). "By performing a ChIP assay, we demonstrated that PRMT5 could occupy the promoter region of FBW7, which was reported to be hypermethylated in cancer cells." (PMID 30922330, 2019). "Since NF-κB has been reported to promote Myc transcription in cancer cells, we hypothesized that NF-κB-driven MYC expression promoted Prmt5 transcription." (PMID 30941147, 2019). "In this review, we will focus on PRMT5, a type II PRMT essential for viability and normal development, which has been shown to be overexpressed in a wide variety of cancer cell types, owing it to the crucial role it plays in controlling key growth regulatory pathways." (PMID 30613353, 2018). "Since the growth/survival effects of PRMT5 inhibitors are time-dependent, the anti-proliferative activity of GSK3203591 was further profiled in a panel of 240 cancer cell lines representing 40 different tumour types in a 10-day growth/death assay." (PMID 29946150, 2018). "Due to the commonality of high levels of PRMT5, our current findings with regards to PDAC and CRC could have broader impacts on the understanding of cancer progression as a whole." (PMID 28591716, 2017).
cancer (continued). "Since PRMT5 is highly expressed in PDAC and CRC, we wondered whether it serves as a tumor promoter in these cancers." (PMID 28591716, 2017). "Our observation that cancer-related pathways are upregulated in HCC upon MYPT1 silencing is the results of the higher expression and hyperactivation of PRMT5, which suppresses gene and protein expression of several tumor suppressors or increasing that of potential oncogenes." (PMID 28074910, 2017). "Based on these analyses, we performed Western blot analysis for proteins of 6 genes whose mRNA expression response to PRMT5/p44 demonstrated the same trend in most (3 out of 4), if not all, cancer cell lines as well as during lung development." (PMID 27480244, 2016). "Both PRMT5 and WDR77 are essential for growth of lung epithelial and cancer cells." (PMID 26988096, 2016). "Similarly, PRMT5 was localized in the nucleus of benign prostate epithelial cells and in the cytoplasm of cells in high-grade PIN and cancer." (PMID 22952863, 2012). "Additionally, MTA accumulation in MTAP-deleted cancers may influence the TME, and PRMT5 has a significant role in T-cell biology." (PMID 40157258, 2025). "Perhaps PRMT5 and MAT2A inhibitors combined with other treatment methods (immunotherapy, chemotherapy, and molecularly targeted therapies) could be considered as first-line therapy for patients with selected cancers." (PMID 41465382, 2025). "In approximately 10-15% of human cancers, deletion of the methylthioadenosine phosphorylase (MTAP) gene results in accumulation of methylthioadenosine (MTA), exposing a synthetic lethality and opportunity for precision medicine by selective targeting of PRMT5 in this context." (PMID 41339334, 2025). "With chemical mastery, we can develop a small molecule that selectively binds to PRMT5 only in the presence of MTA killing tumor cells while sparing healthy ones, which may represent a synthetic lethal‐based precision medicine for patients with these cancers." (PMID 39711357, 2024). "It has been observed that high expression of exosomal circRHOT1 leads to downregulation of miR-204 expression and the gene that regulate this miRNA is Protein arginine methyltransferase 5 (PRMT5), so the miR-204-5p/PRMT5 axis could participate in cancer progression." (PMID 39199587, 2024). "Thus, the activation of STAT3 by the PRMT5/MEP50/STAT3 complex discovered in this study may be a new and specific target for suppressing STAT3 for cancer therapeutic approaches." (PMID 38760429, 2024). "Given the variety of PRMT5 substrates, inhibitors directly targeting PRMT5 might have broad and nonspecific effects in cancer cells and even normal cells." (PMID 39146021, 2024). "Moreover, with ongoing clinical trials of a PRMT5 inhibitor (NCT03614728), our results suggest that assessing ZMYND11 expression levels could enhance the therapeutic potential of PRMT5 inhibition in cancer patients with lower ZMYND11 expression." (PMID 39341825, 2024). "Additionally, pharmacologic inhibition of other methyltransferases (e.g., PRMT5, SMYD3, or MLL4 methyltransferase) or specific deletion of these epigenetic regulators in cancer cells has also been found to specifically increase the antitumor efficacy of anti-PD1 therapy across cancer types." (PMID 39133578, 2024). "Therapeutic targeting of PRMT5 in homozygous MTAP‐deleted cancer cells has thus been considered a promising strategy to selectively killed cancer cells, which predicated on the presence of exceedingly high MTA levels in MTAP‐deleted cancer cells compared to MTAP‐intact tissues." (PMID 39711357, 2024).